TNF (tumor necrosis factor)
Diseases named in the same sentence as TNF in open-access papers (continued):
Sharing a sentence is not in itself a finding about the gene and the disease.
colitis (continued). "Results showed that Shikonin dose-dependently alleviated mice colitis, down-regulated expression of F4/80, iNOS and CD86, decreased IFN-γ, IL-1β, IL-6 and TNF-α, while increased IL-10 in mice colon." (PMID 36059938, 2022). "Its impact on colitis was evidenced by improving the biochemical markers TAC and GSH and the decrease in IL-1β, TNF-α, MDA, and MPO compared to the colitis control group." (PMID 35428860, 2022). "The mRNA expression levels of TNF-α, IL-6, and IL-1β in colon tissue of the DSS-induced colitis group were considerably elevated by the 4% DSS treatment." (PMID 36080669, 2022). "In a chemical-induced mouse model of colitis, L. fermentum CQPC04 reduced TNF-α, IFN-γ, IL-1β, IL-6, and IL-12, and increased IL-10 release in serum; it also downregulated NF-kB and up-regulated IL-10 expression in colon tissue." (PMID 35408849, 2022). "In DSS-induced colitis, mice that were fed experimental diets containing AST (100–200 ppm) exhibited lowered gene expressions of several inflammatory markers including TNF-α, IL-1β, IL-6, COX-2, and iNOS and inhibited NF-κB expression in the colon." (PMID 36555112, 2022). "TNF-α, in turn, directly induces motor dysfunctions by acting on the smooth muscle, as shown in a trinitrobenzenesulfonic acid (TNBS) induced colitis model in mice." (PMID 35630404, 2022). "Our data suggest that pretreatment with Rg1 and ADSC + Rg1 markedly decreases the levels of TLR4 and MyD88, as well as the expression of TNF-α, IL-6, IL-1β, IFN-γ, and IL-17A in the DSS-induced mouse model of colitis." (PMID 35729638, 2022). "TCA treatment during TNBS colitis also resulted in decreased colonic MPO, TNF-α, IL-1β, and INF-gamma levels." (PMID 36569849, 2022). "Increased immunopositivity of TNF-α, vascular endothelial growth factor (VEGF) and CD68 markers was observed in the colitis group cells, and decreased level of this positivity was observed in MSCs treated group." (PMID 36228298, 2022). "Overall, 4 patients died during anti-TNF treatment (1 in ADA group and 3 in IFX group), because of severe colitis or infection." (PMID 35644668, 2022). "Meanwhile, the levels of inflammatory factors TNF-α, IL-1β, and IL-6 were upregulated in DSS-induced colitis mice." (PMID 35630568, 2022). "Our data indicated that SSP inhibits the differentiation of TNF-α+ DCs and MHC-II+ DCs, and increases the secretion levels of IL-10, further rebuilding the balance of GM in colitis mice with SKYD syndromes." (PMID 36310616, 2022). "The main objective of the study was to examine the interaction between the Fc region of the anti-TNF antibody and Fcγ receptors (FcγR), and whether the absence of the Fc core fucose (which increases binding to FcγRIIIa) would increase the effectiveness of anti-TNF against colitis." (PMID 35939430, 2022). "TNF-α as well as CCL2 are also relevant in pathogenesis of IBD as they are released by MC during early stages of inflammation and needed for sustaining colitis." (PMID 35163137, 2022). "SIRT6 transgenic mice showed lower levels of pro-inflammatory cytokines like TNF-a, IL-1β, and IL-6 in the dextran sulfate sodium salt (DSS)-induced colitis model than normal mice." (PMID 35517808, 2022). "Isolated from egg white proteins, MLGATSL, DEDTQAMPFR, DEDTQAMPF, and MSYSAGF significantly inhibited the IL-8 and TNF-α secretion and also down-regulated the mRNA expression of TNF-α, IL-17, IL-6, MCP-1, IL-1β, and IFN-γ in colitis mice." (PMID 35406093, 2022). "In vivo studies assessed the therapeutic effects of penfluridol in various disease models, including TNFα transgenic mice, collagen-induced arthritis, DSS-induced colitis, and TNBS-induced colitis." (PMID 35045889, 2022). "The increased IL-1b and TNF serum levels and enhanced HIF-1 and IL-10 expression in colitis mice were suppressed by CYN therapy, and the treatment facilitated IL-4, CCL2, and PPARγ expression." (PMID 36278202, 2022).
colitis (continued). "Concomitant with colitis development, DCs in inflamed patients increase in number and upregulate the expression of CCR7, TNF, and CXCR3 costimulator molecules." (PMID 35813827, 2022). "In colitis models, oral GDNPs 2 administration increased IEC survival and proliferation, decreased pro-inflammatory cytokines (TNF-α, IL-6, and IL-1), and increased anti-inflammatory cytokines (IL-10 and IL-22)." (PMID 36298592, 2022). "EGCG reduced the levels of TNF-α, IL-6, and NF-κB mRNA expression, NF-κB protein, and MPO activity in colon tissue of rats with trinitrobenzene sulfonic acid (TNBS)-induced colitis." (PMID 35807865, 2022). "CypB expression were positively correlated with expression of IL-6 and TNF-α, suggesting a possible role of CypB in HFD-induced colon inflammation." (PMID 36266267, 2022). "In the present study, we found that the inflammatory cytokines of TNF-α, IL-17, and IFN-γ were up-regulated in the DSS-induced colitis model." (PMID 35761286, 2022). "In this study, we found that SSP can reduce the levels of iNOS+ DCs, TNF-α+ DCs, E-cadherin+ DCs, MHC-II+ DCs, and GM-CSFR+ DCs in colitis mice with SKYD syndromes." (PMID 36310616, 2022). "These T-cell responses can result in effector cytokine production that contributes to the high levels of TNF and IL-6 produced by innate cells in both forms (acute and chronic) of DSS colitis." (PMID 35705557, 2022). "The levels of TNF-α, PTX-3, and MDA were measured in plasma samples, and there was significant increase in colitis group." (PMID 36228298, 2022). "Network of cytokines including IL-1β, TNF-α, IL-6, IL-10, IFN-γ, and IL-18, have been reported to regulate mucosal inflammation in colitis, and IL-6, TNF-α are viewed as therapeutic targets in IBD." (PMID 35330829, 2022). "The pro-inflammatory cytokines TNF-α, IL-1β, IL-6, IL-12, and IFN-γ levels in mice with DSS-induced colitis were apparently higher than those of mice in the normal group, but anti-inflammatory cytokine IL-10 was lower (P < 0.05)." (PMID 36171753, 2022). "Previous studies have shown that niacin attenuates the severity of colitis by decreasing colonic MPO activity, TNF-α, and VEGF levels in a guinea pig model." (PMID 35955466, 2022). "Intriguingly, SPH treatment prevented a significant increase in pro-inflammatory TNF-α and IL-6 and additionally augmented the production of anti-inflammatory IL-10 and TGF-β1 compared with the other two colitis groups (p < 0.01)." (PMID 36139127, 2022). "In an ulcerative colitis model induced by acetic acid in rats, EA administration decreased the protein levels of TNF-α, COX-2, and NF-κB, and thereby exerted protective effects on colonic inflammation." (PMID 35805952, 2022). "In accordance with our study, Th1-derived TNF-α, Th17-derived IL-1β, and IL-6 were significantly increased in DSS-induced colitis mice compared to the control." (PMID 36176442, 2022). "According to the results, plasma TNF-α, PTX-3 and MDF levels were significantly increased in the colitis + saline group compared to the normal control group (p<0.05, p<0.001, and p<0.001, respectively; p< 0.001, p<0.001, and p<0.001 respectively)." (PMID 35894303, 2022). "The expression of TNF-α, IL-6 and IL-1β was substantially upregulated in DSS-induced colitis mice, and treatment with PNU-282987 significantly reduced the enhancement." (PMID 36058917, 2022). "Blocking α2-adrenergic receptors down-regulate TNF and IL-1β and improve 2,4,6-trinitrobenzenesulfonic acid (TNB)-induced colitis." (PMID 35646918, 2022). "The effects of AOS on proinflammatory cytokines were further investigated by ELISA analysis of IL-1β, IL-6, TNF-α, IFN-γ, and IL-10 levels in the serum of DSS-induced colitis mice." (PMID 35889822, 2022). "Accordingly, the increased concentrations of pro-inflammatory cytokines in the colitis mice, such as IL-6, IFN-γ, and TNF-α, were all significantly decreased by SFN treatment." (PMID 35832050, 2022).
colitis (continued). "Based on the results, the gene expression of inflammatory mediators counting TNF-α, IL-1β, and TLR4 noticeably amplified in the colitis group in comparison to the control group (P < 0.05)." (PMID 35432569, 2022). "In our study, except for TNF-α, other pro-inflammatory factors such as IL-6 and IL-1β were also vastly increased in TNBS-induced colitis." (PMID 35571126, 2022). "Notably, a myokine, irisin, has been reported to ameliorate experimental colitis and reduce the colonic TNF-α concentration, suggesting that the skeletal muscle condition is a new treatment target for CD, as well as a predictive marker of the effect of anti-TNF therapy." (PMID 35433773, 2022). "Previous studies demonstrate that there is an increase in TNF-α liberation in acute colitis, and we hereby provide evidence that the P2X3 receptor expression increases in response to DNBS-colitis." (PMID 36032155, 2022). "Through multiplex analysis, we found that DSS induces the release of pro-inflammatory cytokines, IL-1β and TNF-α, which facilitates the inflammation in the DSS-induced colitis mouse model." (PMID 35933374, 2022). "We used qRT-PCR to examine the mRNA expression levels of pro-inflammatory cytokines, including TNF-α, IL-6, and IL-1β, in colon tissue because higher protein and mRNA levels of these cytokines were observed in the DSS-induced colitis animal model." (PMID 36080669, 2022). "The secretion of NO and TNF-α and the accumulation of MPO were also decreased by piperine in colon tissue of mice with acetic acid-induced colitis." (PMID 35807865, 2022). "Although neutralisation of TNF-α had detrimental effects on inflammation during acute DSS-induced colitis, it significantly improved histological scores in chronic DSS-induced colitis." (PMID 36012618, 2022). "Kakkalide, separated from Pueraria lobata, significantly inhibited LPS-stimulated NF-κB activation and TNF-α expression in macrophages and suppressed TNBS-induced colitis in mice." (PMID 36569313, 2022). "GABA inhibits pro-Inflammatory cytokine such as IL-12, IFN-γ, and TNF-α production, while significantly increasing tissue levels of IL-10 in DSS-induced colitis." (PMID 35151255, 2022). "Quantitative analysis showed that the proinflammatory factors secreted by Th1/Th2/Th17, including IL-2, IL-6, TNF-α, IFN-γ and IL-17A significantly increased in the colitis group in both their serum and colonic tissues." (PMID 35372817, 2022). "The effects of roflumilast on serum levels of TNF-α, IL-2, and IL-6 in rats with trinitrobenzenesulfonic acid (TNBS)-induced colitis (n=8)." (PMID 35239781, 2022). "Consequently, we found PYY 3–36 had a protective role in mice with TNBS-induced colitis and this protection might be through inhibiting the production of proinflammatory cytokines TNF-α and IL-6 from activated macrophages and by modulation of the balance of Th1/Th2." (PMID 35443853, 2022). "Similar protective effects against LPS-induced colitis were also observed; IPA protects LPS-induced mice by activating AhR to promote IL-10 production while suppressing the gene expression of TNF-α." (PMID 36159803, 2022). "Our study showed that blockage of BAFF activity effectively inhibited IL-1β, TNF-α, and IL-6 gene expression in colonic tissues from DSS-induced colitis mice." (PMID 35320937, 2022). "In addition, to some degree, different levels of Asp administration decreased the gene expression of TLR4 and MYD88 as well as the TNF-α and IL-6 contents in the UC mice, suggesting that Asp could alleviate colitis in mice by regulating the secretion and expression of inflammatory cytokines." (PMID 36145082, 2022). "It suppressed the inflammatory response via the attenuation of TNF-α, IL-1β, IL-6, and MPO activity in colitis rats in TNBS-induced colitis." (PMID 36235004, 2022). "Next, we found that colitis mice with SKYD syndromes exhibited immune hyperactivity (iNOS+ DCs, TNF-α+ DCs, E-cadherin+ DCs, MHC-II+ DCs, Mac-3+ DCs, and GM-CSFR+ DCs were abnormally activated)." (PMID 36310616, 2022).
colitis (continued). "Increased MPO activity and higher levels of pro-inflammatory factors (TNF-α, IL-1β, and INF-γ) in colitis were significantly reversed by naringin." (PMID 34504431, 2021). "It was found that serum TNF-α, IL-6, IL-18 and IL-1β levels in DSS induced colitis mice model was significantly higher than those in the control normal group." (PMID 34628369, 2021). "Previously, reduced tissue MPO and plasma pro-inflammatory markers (TNF-α, IL-6) were also demonstrated in response to KYNA and SZR-72 treatments in experimental colitis." (PMID 34475875, 2021). "Collectively, cinacalcet reduces production of the inflammatory cytokines TNFα, IL-1β, and IL-6 in a DSS-induced colitis model." (PMID 34880751, 2021). "Cinacalcet significantly reduced both the expression and secretion of TNFα, IL-1β, and IL-6 in the colons of mice with DSS-induced colitis." (PMID 34880751, 2021). "The production of proinflammatory mediators, including IL-1β, IL-6, TNF-α, IL-2, IL-17, and IFN-γ, plays a critical role in DSS-induced colitis in mice." (PMID 34804049, 2021). "The inflammatory cytokines TNF-α and IL-6 are well-known therapeutic targets in IBD that contribute to the deterioration of the colitis condition." (PMID 34630408, 2021). "In a previous study, needle-based VNS decreased the plasma level of TNF-α and IL-6 in a rodent model of 2,4,6-trinitrobenzene sulfonic acid–induced (TNBS-induced) colitis by inhibiting proinflammatory cytokines via the autonomic mechanism." (PMID 34138761, 2021). "In the dextran sulfate sodium (DSS)-induced colitis model, EA suppressed proinflammatory cytokines including IFN-γ, TNF-α, and IL-6." (PMID 35095910, 2021). "The proinflammatory cytokine levels of IL-1β, TNF-α, IL-6, and IFN-γ were increased whereas the anti-inflammatory cytokine IL-10 was decreased in colitis mice." (PMID 33995942, 2021). "The mRNA expression of IL-1β, IL-18, IL-6, TNF-α, IFN-γ, ICAM-1, and VCAM-1 was markedly (all p < 0.01) up-regulated in DSS-induced colitis group, while the IL-10 expression was significantly (p < 0.01) down-regulated." (PMID 33859564, 2021). "Oral administration of Helicobacter typhlonius (phylum Proteobacteria) triggered tumor necrosis factor (TNF)-α and promoted colitis in Tbx21−/−Rag2−/− ulcerative colitis mice." (PMID 33832437, 2021). "Broccoli-derived nanovesicles (BDNs) were able to contrast the increase of pro-inflammatory cytokines, such as TNF-α, IL-17A, and IFN-γ, in colonic tissues of two colitis models (DSS-induced and T cell transfer model of colitis)." (PMID 34065193, 2021). "We also found high red meat intake induced the production of more inflammatory cytokines such as IL-1β, TNF-α, IL-17, and IL-6 and inflammatory inducible enzymes such as COX-2 and iNOS in dextran sulfate sodium-induced colitis." (PMID 34355008, 2021). "Many proinflammatory cytokines, such as IL-6, IL-1β, TNFα, and IL-17, are increased in DSS-induced colitis and UC patients." (PMID 34804049, 2021). "Serum GSH levels decreased, while serum TNF-α, IL-6, and MDA increased significantly in the acetic acid-induced colitis group compared to the normal control." (PMID 33441125, 2021). "RELA+/− mice have similarly impaired NF-κB activation, develop cutaneous ulceration from TNF exposure, and exhibit severe dextran sodium sulfate (DSS)-induced colitis, ameliorated by TNF inhibition." (PMID 34434197, 2021). "On the other hand, IL-27Rα−/− mice developed less severe colitis after DSS treatment when compared to their wild-type controls, characterized by reduction in inflammatory cytokines (IL-6, TNF, and IFN-γ)." (PMID 33435303, 2021). "In the molecular docking model, the structure of mangiferin showed a high binding potential with TNF-α and MMP-9 and a reduced colonic injury partly through attenuating the activity of TNF-α and MMP-9 in the colitis model." (PMID 34066494, 2021).
colitis (continued). "The levels of proinflammatory cytokines, including TNF-α, IL-6, interferon-γ (IFN-γ), interleukin-18 (IL-18) and interleukin-17a (IL-17a), were significantly increased in DSS-induced colitis mice (P < 0.05 vs. CON)." (PMID 34675239, 2021). "In colitis and acute kidney injury models, activation of SIRT1 attenuates the TNFα-mediated intestinal and renal abnormalities." (PMID 33513830, 2021). "Experiments show that transmembrane TNF induces the activation of TNFR2, which intensifies the activity of colitis, and inhibits its function to improve the severity of colitis." (PMID 33553436, 2021). "One week after induction of colitis, rats were assessed by MRC, colon histopathology and inflammation markers (Interleukin 1β, Tumor necrosis factor α, Nitric Oxide Synthase 2 and Cyclooxygenase 2)." (PMID 34735489, 2021). "Berberine can significantly reduce the levels of pro-inflammatory cytokines (TNF, IFN-γ, KC, IL-7) in colon tissue and improve the symptoms of intestinal injury and colitis model induced by dextran sulfate sodium in mice." (PMID 34594213, 2021). "Antibiotic-treated mice receiving melatonin-treated feces showed marked relief of Oxa-induced colitis, including weight loss, colonic shortening, and histological severity, which coincided with a decrease in the level of the inflammatory cytokine TNFα, but not in the level of IL-1β, in the colon." (PMID 35116024, 2021). "Therapeutic efficacy of MSCs thus is improved in type IV hypersensitivity, liver injury, colitis, graft-versus-host disease, and arthritis via interferon (IFN)-γ or tumor necrosis factor (TNF)-α combined with interleukin (IL)-1." (PMID 34505627, 2021). "In the sedentary colitis mice fed either SD or HFD, the mRNA expression of TNF-α, IL-1β and IL-6 was significantly increased compared with the respective values obtained in the group of non-exercising (sedentary) animals fed an SD (p < 0.05)." (PMID 33557311, 2021). "The main cellular mechanism of Res resistance to dextran sodium-sulphate-induced colitis is achieved by down-regulating the expression of inflammatory molecules such as IL-6, IL-1β, IFN-α and TNF-α." (PMID 34944291, 2021). "However, A20 IEC-KO mice were more susceptible to experimental colitis and had increased IEC apoptosis, while A20Myeol-KO mice developed rheumatoid arthritis-like symptoms due to excessive activation of myeloid cells to produce high levels of pro-inflammatory cytokines, including TNF-α/IFN-γ." (PMID 34956195, 2021). "Oral administration of acacetin increased the production of iNOS, COX-2, IL-6, TNF-α and IL-1β in mice with DSS-induced colitis." (PMID 33806061, 2021). "We showed that FAHF-2 suppresses TNF-α, IFN-γ, IL-1β, IL-6, IL-12 and IL-17 production from both PBMCs and inflamed colonic mucosa from pediatric subjects with CD, and abrogates murine colitis in the CD45RBhi transfer model." (PMID 34926527, 2021). "The authors further verified that the administration of micheliolide strongly inhibited IL-6, TNF-α, and IL-1β expression in a murine model of DSS-induced colitis." (PMID 34208907, 2021). "In the model of murine colitis, TNFR1 is highly expressed in intestinal epithelial cells and mediates TNFα induced inflammatory cascades." (PMID 33513830, 2021). "On the other hand, in vivo, CC NLCs alone decreased the TNF-α secretion and neutrophil infiltration and reduced the inflammation in a DSS-induced murine colitis model." (PMID 33918207, 2021). "Many of the colitis-induced cytokines that we found to be influenced by the FAAH SNP (e.g., IL-2, LIF, MCP-1, and TNF), have been found to be regulated by FAAH inhibition in other studies." (PMID 34916909, 2021). "It has been reported that proinflammatory cytokines such as IL6 and TNF-α and inflammatory mediators such as NO rise in primary stages of TNBS-induced colitis in rats." (PMID 33505492, 2021). "The phenotype named Colitis contains seven DEGs from our lists: IL10, IL11, IL1B, IL1RN, IL6, MIF and TNF." (PMID 34680872, 2021).